IL23R (interleukin 23 receptor)
Diseases named in the same sentence as IL23R in open-access papers (continued):
Sharing a sentence is not in itself a finding about the gene and the disease.
leprosy (13 papers, 2013 to 2025). Leprosy is a chronic infectious disease affecting primarily the skin and peripheral nervous system. "As observed in this study, it was not possible to identify an association between the SNP rs3762318 in the IL23R gene and the operational classifications of leprosy (ORAA = 1.87, p = 0.30)." (PMID 41430577, 2025). "This study evaluated the association of polymorphisms in the CCDC122-LACC1 (rs4942254) and IL23R (rs3762318) genes with leprosy in two populations from Northeastern of Brazil." (PMID 41430577, 2025). "The IL23R gene has been shown to be a candidate gene for association with leprosy, since SNPs in this gene have been associated with increased susceptibility to the disease, also affecting the profile of inflammatory cytokines in human cells." (PMID 41430577, 2025). "Pertaining to infectious diseases, IL23R polymorphisms have been reported in association with viral infections, leprosy, and related manifestations." (PMID 37464360, 2023). "Two IL-23/Th-17 pathway genes, IL12B encoding the heterodimeric subunit of IL-23 and IL23R encoding the IL23 receptor, were identified as leprosy susceptibility genes in different populations." (PMID 32373110, 2020). "An increase in the copy number of exon 11 in the IL23R gene has been reported to be associated with the paucibacillary form of leprosy." (PMID 26626589, 2015). "The IL23R gene encodes the protein responsible for forming a receptor for the cytokine interleukin (IL)-23, and is part of the signaling pathway involving the gene product from another locus associated with leprosy, TNFSF15." (PMID 41430577, 2025). "The aim of this study was to investigate whether polymorphisms at CCDC122-LACC1 and IL23R genes have genetic influences on the development of leprosy in two populations from Northeastern Brazil." (PMID 41430577, 2025). "To validate whether enhanced IL-6R expression on CD4+ T cells is causative of elevated IL-17A response in T1R leprosy patients, we studied the effect of blocking of IL-6R and IL-23R in MLSA induced IL-17A production by PBMCs cells in-vitro." (PMID 32934336, 2020). "However, we cannot rule out the possibility of other rare or common variants of IL23R or TYK2 being related to leprosy susceptibility in the Amazon population." (PMID 32433683, 2020). "Of interest, a very recent study demonstrated IL23R variants as susceptibility variants for leprosy and suggested a potential involvement of IL23R in the autophagocytosis of mycobacteria involved in the pathogenesis of leprosy." (PMID 23365659, 2013). "Within compared with the findings in the literature, a study that analyzed the numbers of copy variations of the IL23R gene showed a significant increase in copies in PB patients (PB = 36.4%; Controls = 20.2%; p = 0.026), positively associating the gene to the PB form of leprosy." (PMID 41430577, 2025). "Subsequently, IL-6R and IL-23R blocking experiments showed significantly (p < 0.002) down regulated IL-17A in T1R reaction as compared to NR leprosy patients." (PMID 32934336, 2020). "On the other hand, IL-23R+IL-17A+ T cells were found to be insignificant between T1R (1.3 ± 0.6) and NR (1.0 ± 0.8) leprosy patients." (PMID 32934336, 2020). "IL-23, CCL20 required for maintenance of Th17 cells and IL23R also showed enhanced expression in leprosy reactions as compared to the respective non reactive groups." (PMID 27035913, 2016). "Taken together our data supports the greater role of IL-23 and its ligand IL-23R in leprosy as compared to IL-6/IL-6R for IL-17 production in both circulating cells and at the site of the dermal lesions." (PMID 23936569, 2013). "Here, we investigated whether SNPs located in eleven genes: CCDC122/LACC1, IFNG, IL6, IL10, IL23R, LRRK2, NOD2, PACRG/PRKN, TLR1, TNF and TYK2 are associated to leprosy susceptibility in a population in the North of Brazil." (PMID 32433683, 2020).
leprosy (continued). "Surprisingly, the association of IL-23R and not IL-6R with IL-17+ cells in NR leprosy patients is not well studied." (PMID 32934336, 2020). "It appears that IL-23R was more relevant in leprosy than IL-6R reported to function in a similar manner indicating that the pathway of Th17 may show subtle differences not only in man as compared to the mouse but also in different diseases." (PMID 23936569, 2013). "Thus, the leprosy susceptibility loci, including NOD2, RIPK2, TNFSF15, LACC1, LRRK2, IL12B, and HLA‐DR in phagocytes and IL23R, TYK2, and CSK in T cells, may interfere with the synergistic antimicrobial response between phagocytes and T cells." (PMID 38020709, 2023). "Of interest, gene expression of IL-6R and IL-23R in T1R and NR patients in 48 h MLSA stimulated PBMC showed a significant increase (p < 0.01, p < 0.002) in T1R as compared with NR leprosy patients." (PMID 32934336, 2020). "After checking the status of IL-6R+ and IL-23R+ Th17 cells in reactional states, we were next interested in the secretion status of IL-17 via Th17 cells with or without MLSA, r-IL-6, r-TGF-β and r-IL-23 in both T1R and NR leprosy patients." (PMID 32934336, 2020). "Indeed, while several genes with known overlap of IBD and leprosy were detected (i.e. RIPK2, LACC1 and IL23R), there was no genome-wide statistical enrichment for IBD risk alleles in T1R-free leprosy (p = 0.09)." (PMID 28222097, 2017). "However, CD4+IL23R+ cells were detected without any difference between T1R and NR leprosy patients." (PMID 32934336, 2020).
breast cancer (10 papers, 2012 to 2024). A primary or metastatic malignant neoplasm involving the breast. "In order to evaluate the influence of IL-23R gene polymorphisms on the susceptibility to sporadic breast cancer, a case–control study was conducted on a cohort of Chinese Han women." (PMID 39796684, 2024). "The C allele of rs10889677 A > C polymorphism in the 3′-UTR of IL23R is associated with breast cancer, lung cancer, and nasopharyngeal carcinoma in Chinese individuals; the A allele eliminates miR-let-7f binding sites, thereby increasing IL23R transcription." (PMID 29299175, 2017). "Only the rs10889677 SNP, located at the 3′-UTR of the IL23R gene, was associated with the risk of breast cancer." (PMID 23239971, 2012). "In our case-control study, for the first time we investigated the association between two SNPs in IL23R gene and the risk of sporadic breast cancer in Chinese Han women." (PMID 23239971, 2012). "The miRNA binding site in the SNP affects IL23R expression and is associated with breast cancer." (PMID 33505778, 2021). "Our results suggest that a miRNA binding site SNP in the 3′-UTR region of the IL23R gene may be associated with the risk of breast cancer and contribute to the early development of breast cancer in Chinese women." (PMID 23239971, 2012). "Therefore, we investigated the influence of the IL23R gene polymorphisms in the pathogenesis of breast cancer." (PMID 23239971, 2012). "Thus it seemed logical that the AA genotype and the A allele led to the loss of a regulatory miRNA site and increased the IL23R expression, and then increased the risk of breast cancer." (PMID 23239971, 2012). "Frequencies of genotypes and alleles of two IL23R SNPs in breast cancer patients and controls." (PMID 23239971, 2012). "The association of IL23R SNPs with breast cancer was further analyzed with the Haploview program." (PMID 23239971, 2012). "Thus, our study reveals a novel SNP in the IL23R gene that may be associated with the risk and the early age of onset of sporadic breast cancer." (PMID 23239971, 2012). "Gene expression levels of the IL-23R gene are notably higher in breast cancer tissues and positively correlated with tumor size, TNM stage and metastasis in patients." (PMID 39796684, 2024). "The IL-23/IL-23R pathway may therefore be a potential prognostic marker and target for the treatment of breast cancer patients." (PMID 39796684, 2024). "Many studies have shown that IL-23R plays a crucial role in tumorigenesis and cancer development in different types of cancer, such as esophageal cancer, colorectal cancer, bladder cancer, breast cancer, and laryngeal cancer." (PMID 34412691, 2021). "We genotyped two tag SNPs (rs10889677 in the 3′-UTR region and nonsynonymous variants rs1884444 in exon 2) in IL23R gene of 491 breast cancer patients and 502 matched healthy controls." (PMID 23239971, 2012). "To date, no studies have investigated the association between IL23R gene polymorphism and human breast cancer." (PMID 23239971, 2012). "In addition to its role in SCC, IL-23 promotes tumor progression by the inhibition of apoptosis in breast cancer cell lines, and levels of IL-23 and IL-23R expression are positively correlated with tumor size, tumor-node-metastasis stage, and metastasis in breast cancer." (PMID 33178182, 2020). "But presently, no studies evaluated the association between IL23R SNPs and the breast cancer risk." (PMID 23239971, 2012). "We hypothesized that IL23R may affect the development of breast cancer." (PMID 23239971, 2012). "STAT3 activation by IL-23/IL23R and via IL-32β-induced VEGF leads to increased migration and invasion of breast cancer (BC) and gastric cancer (GC) cells." (PMID 31952344, 2020).
spondyloarthritis (10 papers, 2013 to 2025). "First, the finding of similar IL-23R + cells in multiple characteristic spondyloarthritis sites even prior to disease initiation, outside typical immune system tissues, suggested immune cells are already present, just awaiting a trigger to secrete cytokine." (PMID 40938333, 2025). "In this model, they used an IL-23R-GFP reporter transgene to identify IL-23 responsive tissue-resident cells in spondyloarthritis prone areas such as the uveal tract, enthesis, and aortic root." (PMID 40938333, 2025). "Entheseal IL-23R+ γδ T cells expressing high levels of IL-23R transcripts, have been observed to be enriched in the joints of spondyloarthritis patients." (PMID 39796684, 2024). "Functional polymorphisms in genes regulating the innate immune response against fungi have been associated with spondyloarthritis (CARD9 and IL23R)." (PMID 29675414, 2018). "Additionally, ILC3 cells in the synovial tissue of patients with spondyloarthritis demonstrate expression of RORC and IL-23R and respond to IL-23 by expressing IL-22." (PMID 39796684, 2024).
gastric cancer (9 papers, 2014 to 2025). A primary or metastatic malignant neoplasm involving the stomach. "In fact, studies have shown that IL-23R polymorphisms are associated with susceptibility to gastric cancer." (PMID 24586528, 2014). "This study aimed to investigate the associations between dietary mercury and gastric cancer (GC) and to determine whether the IL23R rs10889677 polymorphism, located within a predicted binding site for microRNA-lethal-7, may modify these associations." (PMID 38810984, 2024). "In the context of gastric cancer, IL-23R polymorphisms were also investigated." (PMID 39796684, 2024). "In gastric cancer, higher expression levels of IL-23R were found and its expression was seen to be positively correlated with tumor size and poor clinical prognosis." (PMID 40297579, 2025). "A significant correlation was also observed between IL-23R-positive gastric cancer tissues and larger tumor size, worse T stage and poorer clinical prognosis." (PMID 39796684, 2024). "The aim of this study was to identify the associations between dietary mercury and gastric cancer (GC) and to investigate whether the IL23R rs10889677 polymorphism modifies those associations." (PMID 38810984, 2024). "An increased level of positive expression of IL-23R was observed in the tissues and cell lines of the gastric cancer." (PMID 39796684, 2024). "In certain types of cancer, such as colorectal and gastric cancer, the chronic inflammation induced by the IL-23R pathway can create an environment that is conducive to tumor growth." (PMID 39796684, 2024).
colorectal cancer (8 papers, 2014 to 2025). A primary or metastatic malignant neoplasm that affects the colon or rectum. "In the context of inflammation-associated colorectal cancer, there is evidence that IL-23R signaling in Treg cells has an inhibitory effect on carcinogenesis." (PMID 39796684, 2024). "The evidence would suggest that IL-23R signaling in tumor-associated regulatory T cells has opposing effects in murine models of sporadic colorectal cancer and inflammation-associated colorectal cancer." (PMID 39796684, 2024). "In the let-7 binding site of interleukin 23 receptor (IL23R) mRNA, rs10880677 A > C polymorphism was described as a potential screening biomarker for colorectal cancer (CRC)." (PMID 35628648, 2022). "Hereafter, we suggest that IL17A G197A, IL17F rs763780and IL23R rs10889677 polymorphisms are associated with the development and progression of colorectal cancer." (PMID 26083022, 2015). "Previously, we showed that there is a significant association between IL17A, IL17F and IL23R polymorphisms as well as the occurrence of colorectal cancer and the clinical features of the disease." (PMID 26083022, 2015). "In light of these results, we additionally studied the association between polymorphisms in IL17F, IL17A and IL23R genes and different types of colorectal cancer treatment." (PMID 26083022, 2015). "The purpose of the present work is to investigate an association between IL17A, IL17F and IL23R polymorphisms in 102 Tunisian patients with colorectal cancer treatment." (PMID 26083022, 2015). "Recently, we hypothesized that Th17 cells can contribute to carcinogenesis and that IL17A, IL17F and IL23R polymorphisms can affect the susceptibility to colorectal cancer." (PMID 26083022, 2015). "It was reported to play a paramount role in the mucosal immune system, as the IL-23 receptor (IL-23R) is expressed specifically in colorectal carcinoma (epithelial) cells." (PMID 40149674, 2025). "Despite the long-standing association between regulatory T cells (Tregs) and a poor prognosis in solid tumors, the role of IL-23R signaling in Tregs in colorectal cancer remains poorly characterized." (PMID 39796684, 2024). "Conversely, in sporadic colorectal cancer, IL-23R signaling in Treg cells has been observed to have a promoting effect on carcinogenesis." (PMID 39796684, 2024). "A significant number of studies have demonstrated the presence of IL-23R in human colorectal cancer tissue samples." (PMID 39796684, 2024). "In general, the genes encoding the cytokines are genetically polymorphic and polymorphisms in genes IL23R and IL17 have been proved to be associated with its susceptibility to inflammatory diseases as well as cancer including colorectal cancer." (PMID 26083022, 2015). "This was accomplished by first investigating IL-23p19, IL-23p40 and IL-23R in normal colonic tissue, matched adenomas, carcinomas and lymph node metastases from a well-characterized cohort of colorectal cancer patients." (PMID 25015728, 2014). "In a first step, differences in expression of IL-23R, IL-12p40, IL-23 and nuclear IL-23p19 between normal tissues, adenomas, primary colorectal cancers and lymph node metastases were investigated." (PMID 25015728, 2014). "Here we analyse the expression of IL-23 subunits (p40 and p19) and IL-23R in colorectal cancer with regard to disease progression, clinical-pathological and molecular aspects." (PMID 25015728, 2014). "Our study using matched normal-adenoma-carcinoma and lymph node metastases underlines the possible role of IL-23/IL-23R in the early, rather than late progression of colorectal cancers." (PMID 25015728, 2014). "Here we showed that IL23R variant could increase the susceptibility to colorectal cancer unlike IL17F polymorphism which could confer protection against this cancer." (PMID 26083022, 2015). "In conclusion, IL-23 and IL-23R may play a role in early colorectal cancer progression." (PMID 25015728, 2014).
colorectal cancer (continued). "As EMT plays important roles in promoting stem cell transformation and chemoresistance and IL-23R was abundantly expressed in colorectal cancer cells, we wondered if IL-23 mediated the chemoresistance and EMT of colorectal cancer." (PMID 37781363, 2023). "Immunohistochemistry for IL-23p19, IL-23p40, IL-23R and CD8 was performed on a multi-punch tissue microarray of 195 colorectal cancers (cohort 1), matched normal tissue, adenoma and lymph node metastases." (PMID 25015728, 2014). "Through case / control studies, we have recently showed that unlike IL17F rs763780 and IL23R rs10889677 polymorphisms, IL17A G197A polymorphism is associated with its susceptibility to colorectal cancer." (PMID 26083022, 2015). "The aim of this study was to determine the expression of IL-23 (p19 and p40) and IL-23R in the progression of colorectal cancers through the adenoma-carcinoma-metastasis sequence, relationship to intratumoural CD8+ T-cells and impact on overall survival in patients with colorectal cancer." (PMID 25015728, 2014).
colon carcinoma (6 papers, 2012 to 2024). "To confirm that IL17F rs763780and IL23R rs10889677 polymorphisms were associated with the tumor location, we evaluate the relationship between colon cancer susceptibility and these two polymorphisms." (PMID 26083022, 2015). "Association between IL17F/IL23R polymorphisms and colon cancer." (PMID 26083022, 2015). "The role of IL-23R signaling in Treg cells in sporadic CRC was examined utilizing orthotopic injection of the syngeneic colon cancer cell line MC-38 submucosally into the colon/rectum of mice." (PMID 38375204, 2023). "Also, IL23R mRNA level was upregulated in a colon carcinoma cell line showing up to 90% cells with NAV3 deletion." (PMID 22173670, 2012). "Our results indicate that IL-23R signaling in colon tumors is active in non-epithelial cells, likely infiltrating immune cells, but the causal effects of Treg cell-specific IL-23R signaling requires additional studies in humans to understand the implications in CRC pathogenesis." (PMID 38375204, 2023). "We observed a significant increase in the expression level of IL-23A and its receptor IL-23R in colon cancer tissues of humans, and AOM treated rat colon cancer model when compared with matched normal mucosa." (PMID 34680308, 2021). "Indeed, IL17F AG+GG mutated genotypes could protect against colon cancer unlike IL23R AC+AA mutated genotypes that could increase the susceptibility of colon cancer." (PMID 26083022, 2015).